QRICH2 (glutamine rich 2)
Description:
Has an essential role in the formation of sperm flagella and flagellar structure maintainance. It acts as a suppressor of ubiquitination and degradation of proteins involved in flagellar development and motility.
Synonyms: DKFZP434P0316; SPGF35
Tractability: No criterion of Open Targets' tractability assessment is met for any kind of drug.
Gene: Protein-coding gene on chromosome 17 (76,274,049 to 76,308,276, reverse strand). Ensembl gene ENSG00000129646.
Subcellular location: Nucleus membrane; Nucleus; Cytoplasm; Cell projection, cilium, flagellum
Subcellular location (Human Protein Atlas): Nuclear membrane; Nucleoplasm; Vesicles
Gene Ontology:
Molecular function: protein binding
Biological process: cell projection assembly; flagellated sperm motility; negative regulation of ubiquitin-dependent protein catabolic process
Cellular component: sperm flagellum; cytoplasm; nuclear membrane; nucleus; motile cilium
Genetic constraint (gnomAD): Loss-of-function variants: 119 observed, 166.56 expected, observed/expected ratio (o/e) 0.71, 90% interval 0.62 to 0.83. The upper end of that interval is the gene's LOEUF score, 0.83, which puts it in group 3 of 6, group 1 being the genes least tolerant of losing a copy. Missense variants: 2,225 observed, 2,501.8 expected, observed/expected ratio (o/e) 0.89, 90% interval 0.86 to 0.92. Synonymous variants: 888 observed, 955.65 expected, observed/expected ratio (o/e) 0.93, 90% interval 0.88 to 0.98.
Homologues: Orthologues: chimpanzee QRICH2 (93% identical), macaque QRICH2 (85% identical), dog QRICH2 (65% identical), rabbit QRICH2 (61% identical), pig QRICH2 (58% identical), rat Qrich2 (54% identical), mouse Qrich2 (50% identical). Paralogues in human: C16orf96 (12% identical), ZP1 (4% identical), ZP2 (4% identical), ZP4 (4% identical).
Diseases named in the same sentence as QRICH2 in open-access papers:
QRICH2 is named in the same sentence as 9 diseases in open-access papers, as found by Europe PMC text mining. Sharing a sentence is not in itself a finding about the gene and the disease. The quoted sentences say what the papers report.
male infertility (7 papers, 2019 to 2024). The inability of the male to effect fertilization of an ovum after a specified period of unprotected intercourse. "QRICH2 (glutamine rich 2) is located on human chromosome 17 and has been reported to be associated with sperm flagella development and male infertility." (PMID 38243319, 2024). "In our prior investigation, we discerned loss-of-function variants within the gene encoding glutamine-rich protein 2 (QRICH2) in two consanguineous families, leading to various morphological abnormalities in sperm flagella and male infertility." (PMID 38597976, 2024). "Reduced AKAP4 and QRICH2 protein levels cause dysplasia of the fibrous sheath, which ultimately leads to decreased sperm motility and male infertility." (PMID 37174638, 2023). "Our findings strongly suggest that the genetic mutations of human QRICH2 can lead to male infertility with MMAF and that QRICH2 is essential for sperm flagellar formation." (PMID 30683861, 2019). "The screening of the deleterious mutations of QRICH2 could be important for clinical molecular diagnosis of male infertility." (PMID 30683861, 2019). "It is the first time that QRICH2 has been identified to cause MMAF in humans, providing a new genetic diagnostic cue for male infertility." (PMID 30683861, 2019). "A recent study proved that QRICH2 is a functional molecule essential for sperm flagellum development by regulating the genes associated with the flagellum accessory structures, and mutations in this gene resulted in MMAF and male infertility both in men and mice." (PMID 35886074, 2022).
Infertility (4 papers, 2019 to 2024). "Our previous study identified two nonsense mutations of QRICH2 in infertile patients from two consanguine families that caused degradation and loss of function of the QRICH2 protein." (PMID 38597976, 2024). "Here, we identify and functionally characterize homozygous loss-of-function mutations of QRICH2 in two infertile males with MMAF from two consanguineous families." (PMID 30683861, 2019). "Human and mouse orthologs of the QRICH2 gene harbour loss-of-function variants that result in multiple morphological abnormalities and ultrastructural defects of the sperm flagella, thereby leading to immotile sperm and infertility in vivo." (PMID 35255804, 2022). "We then generated the Qrich2 KO mice and found similar sperm phenotype to the patients, i.e., the KO mice were infertile." (PMID 38597976, 2024). "Additionally, Qrich2-deficient male mice showed MMAF phenotypes and infertility." (PMID 30683861, 2019).
asthenospermia (2 papers, 2019 to 2024). "Given that the reduced sperm motility in Ht mice closely resembles the sperm phenotype of human asthenospermia, these data suggest that the deleterious heterozygous mutations of human QRICH2 may contribute to asthenozoospermia." (PMID 30683861, 2019). "Thus so, the pathologic heterozygous variants of QRICH2 could increase the risk for asthenozoospermia." (PMID 30683861, 2019). "Consequently, we suppose that whether QRICH2 mutations are associated with asthenospermia." (PMID 30683861, 2019). "To investigate the variation of QRICH2 in interfile males with asthenospermia, we sequenced all 18 exons and their flanking intronic regions of QRICH2 in 150 asthenospermia patients." (PMID 30683861, 2019). "Furthermore, our results showed that the upper sperm displayed higher glutamylation levels of tubulin and expression of Qrich2, and the patients with asthenospermia manifested a lower level of tubulin glutamylation in sperm." (PMID 38597976, 2024).
breast carcinoma (1 paper, 2024). "MUC4, QRICH2 and PR1L1 mutations were also detected in breast invasive carcinoma databases (TCGA, Cell 2015; TCGA, Nature 2012), but no further research or relationship between these genes and breast carcinomas were published." (PMID 38243319, 2024).
breast invasive carcinoma (1 paper, 2024). "MUC4, RP1L1 and QRICH2 mutations were identified in at least three tumors, and these mutation also existed in breast invasive carcinoma databases (TCGA, Cell 2015; TCGA, Nature 2012)." (PMID 38243319, 2024).
meningioma (1 paper, 2024). A generally slow growing tumor attached to the dura mater. "Only one case report mentioned that deleterious mutated genes such as QRICH2 could occur in meningioma." (PMID 38243319, 2024).
QRICH2 also shares sentences with these, for which no sentence is quoted: cancer (2 papers); epilepsy (1); testicular embryonic carcinoma (1).